C3 (complement C3)
Diseases named in the same sentence as C3 in open-access papers (continued):
Sharing a sentence is not in itself a finding about the gene and the disease.
multiple sclerosis (30 papers, 2009 to 2026). A progressive autoimmune disorder affecting the central nervous system resulting in demyelination. "It has been recently proposed that C3-dependent microglial priming confers susceptibility in multiple sclerosis, resulting in microglial over activation in response to secondary insults." (PMID 28978173, 2017). "Previous studies have reported that activation of the complement system is associated with the pathogenesis of multiple sclerosis, and complement C3 may play a crucial pathogenic role in multiple sclerosis." (PMID 39087011, 2024). "Although we did not examine the expression of C1q in microglia, we studied the expression of CD68 expression in microglia since C3-positive reactive astrocytes have been found to be in close association with CD68-positive microglia in other neurodegenerative diseases such as multiple sclerosis." (PMID 38025259, 2023). "Complement system modulation: targeting complement proteins (e.g., C3 and C5 inhibitors) is a promising approach to limit excessive immune activation, particularly in conditions like multiple sclerosis." (PMID 40260075, 2025). "The products of C3 and Lrp1 were also shown to play a role in pathogenesis of multiple sclerosis or EAE and the product of Nrp2 is involved in the remyelinating process in demyelinating lesions." (PMID 36817487, 2023). "In another study, two factors involved in complement activation, clusterin and C3, were identified in the CSF of several patients of multiple sclerosis." (PMID 28326060, 2017). "Elevated levels of complement components such as C1q and C3 have also been found in EVs from other inflammatory conditions, like multiple sclerosis and ischemic stroke, which may indicate a shared pathway of immune‐mediated damage." (PMID 40465195, 2025). "Furthermore, a mouse model of multiple sclerosis with increase of C1q and C3 in the brain has shown that knock-out of C3 protected against synaptic loss, while little improvement was found in C1q knock-out mice." (PMID 38427092, 2024). "Similarly, Werneburg and colleagues also used Crry, but fused it to a domain of CR2, which binds activated C3, in the context of multiple sclerosis." (PMID 38817607, 2024). "On the other hand, the OL_7 subcluster expressed markers of immune cells such as C3, CD74, and CD83, therefore sharing a common transcription profile with the ImOLG population described in multiple sclerosis." (PMID 40293058, 2025). "The impact of the interaction between C3 fragments and CR3 on microglia priming has been recently demonstrated in a multiple sclerosis model." (PMID 23206327, 2012). "For C2, C3, and C4 levels, the mean and STD of each metric for healthy volunteers, for multiple sclerosis (MS) patients with or without lesions, and MS patients with lesions >5% and >10%." (PMID 37775975, 2023).
melanoma (29 papers, 2013 to 2026). A malignant, usually aggressive tumor composed of atypical, neoplastic melanocytes. "To investigate TME mediators implicated in the modulation of C3 in MAMCs, we have used the supernatants of cultured melanoma cell lines RPMI-7951 and A375 to condition blood-derived MCs." (PMID 35669782, 2022). "Thus, our findings demonstrate the plasticity of human MCs in a tumor context, show that specific mediators in the melanoma microenvironment dictate their phenotype, and underline the prognostic impact of C3+ MCs in melanoma." (PMID 35669782, 2022). "C1q-deficient (C1qa−/−) mice, bearing a syngeneic B16 melanoma, exhibited slower tumor growth and prolonged survival, compared to C3 or C5 deficient mice although it has been shown that C3/C5 deficiency may also create microenvironment suboptimal for tumor growth." (PMID 31130944, 2019). "The NK1/C3 antibody is noteworthy for its ability to identify a specific cytoplasmic antigen prevalent in melanoma cells." (PMID 37958863, 2023). "C3 mRNA expression was more prominent in 3T3-L1 cells (50-60-fold/B16 melanoma) and was upregulated essentially in response to IFN-γ, a cytokine known to be released by intra-tumoral T cells." (PMID 37296948, 2023). "In the present study, we provide evidence that the melanoma micromilieu enhances the production of CCL2, IL-8, IL-1β, and C3/C3a by MCs, factors associated with tumor progression." (PMID 35669782, 2022). "Triple immuno-staining detecting melan-A (MelA) (tumor area), tryptase (MAMCs), and C3 was performed on slides obtained from melanoma lesions and healthy skin biopsies and tryptase+ C3+ MAMCs were counted." (PMID 35669782, 2022). "In melanoma, 24% of MAMCs (SD: 20, n = 11) expressed C3 compared with 7% of C3+ MCs in healthy skin (SD: 6, n = 10)." (PMID 35669782, 2022). "Most importantly, a higher expression of TPSAB1 and C3 significantly correlated with poorer patient survival [log-rank (Mantel–Cox) p < 0.05], thus supporting the prognostic impact of C3+ MCs in melanoma." (PMID 35669782, 2022). "This confirms the relevance of MCs for C3 expression in melanoma and is entirely in line with previous data from scRNA-seq demonstrating that C3 expression in the melanoma TME comes from the immune cell population." (PMID 35669782, 2022). "Previous work by Janelle and colleagues demonstrated that the depletion of the complement C3 in melanoma-bearing mice, resulted in an increase infiltration of NK cells within the TME and subsequent tumor growth delay." (PMID 35937458, 2022). "C3, secreted and cleaved extracellularly to C3a and C3b, triggers C3a-C3aR signalling, resulting in increased neutrophil infiltration of tumors in mouse B10 melanoma." (PMID 35860237, 2022). "Most importantly, we found a significant correlation between the increase of C3+ MC numbers, disease severity (melanoma stage IV), and poor prognosis." (PMID 35669782, 2022). "Similar pattern of C3 expression in stromal cells and C3aR in macrophages was found in human melanoma and head and neck tumors." (PMID 35860237, 2022). "A significant increase in C3+ MAMC (tryptase+ C3+) numbers was observed in melanoma (mean: 58.72 cells/mm2, SD: 43.64, n = 82) compared with tryptase+ C3+ healthy skin MCs (mean: 21.25 cells/mm2, SD: 9.85, n = 10)." (PMID 35669782, 2022). "In summary, C3 seems to be a key complement component highly expressed in the TME, and C3a, the C3-derived anaphylatoxin (C3a), is induced in MCs by melanoma-conditioned medium." (PMID 35669782, 2022). "Altogether, the data support the concept that C3 is a key mediator in melanoma, but importantly, MCs in the presence of tumor cell-secreted mediators, such as cytokines, have the ability to synthesize C3 and cleave it to C3a." (PMID 35669782, 2022). "Most importantly, we found a significant correlation between the increase of C3+ MC numbers, increase of disease severity, and poor prognosis, suggesting a prognostic impact of C3+ MCs in melanoma." (PMID 35669782, 2022).
melanoma (continued). "As demonstrated in this study, both EMT6 and 4T1 cells express C3 mRNA, and at levels that are relatively higher than other murine cell lines, such as B16 melanoma, MC38 colon carcinoma and Lewis lung carcinoma (LLC)." (PMID 33430104, 2021). "We found that C3, C3AR1, and C5AR1 are associated with T-cell dysfunction phenotypes in two (GSE12417_GPL570 and TCGA melanoma) of the five datasets enumerated." (PMID 34439277, 2021). "High C3 expression was associated with a good outcome of ICB therapy of PD1, CTLA4, and ACT in melanoma but was associated with worse PD and PDL1 outcomes in GBM and bladder cancer, respectively." (PMID 34439277, 2021). "Surprisingly, the authors did not observe the impact of C3 deficiency on the growth of B16 tumors, which was inconsistent with reports documenting the role of C3 in the same murine model of melanoma." (PMID 33271774, 2020). "The NK1/C3 antibody was synthesized at the Netherlands Cancer Institute, and although its target antigen was not initially known, it appears to be a glycoprotein located on the membranes of cytoplasmatic vesicles in melanoma cells." (PMID 37958863, 2023). "In stage III of melanoma, we observed higher C3+ MAMC numbers (35.6 cells/mm2, SD: 20.4, n = 15)." (PMID 35669782, 2022). "However, in the melanoma tissues, we also observed a few tryptase− C3+ cells (3.67 cells/mm2, SD: 5.76, n = 82)." (PMID 35669782, 2022). "Furthermore, we observed a higher C3+ MAMC number in the latest melanoma stage and a significantly worse survival rate in melanoma patients expressing a higher level of combined TPSAB1 and C3 mRNA." (PMID 35669782, 2022). "Therefore, we investigated the expression of complement components C1R, C1S, C5, and C3 by qRT-PCR in MCs treated with melanoma cell-derived conditioned medium." (PMID 35669782, 2022). "Thus, our histochemistry data confirm the changes in C3 expression detected by RNA-seq and altogether suggest that MAMCs contribute to C3 expression in the melanoma TME and higher numbers of C3+ MCs correlate with disease severity." (PMID 35669782, 2022). "However, C3 was detected with variable expression among MelA+ cells in the same biopsy, with 39% of melanoma tissue displaying less than 1% of MelA+ C3+ cells and 11% melanoma biopsies with equal or greater than 1% MelA+ C3+ cells." (PMID 35669782, 2022). "Furthermore, in melanoma tissue, we observe a significantly increased number of C3+ MCs in stage IV melanoma." (PMID 35669782, 2022). "In-vitro MCs exposed to melanoma cell supernatants upregulate C3 expression." (PMID 35669782, 2022). "Thus, degradation of bound C3b by a C3-cleaving serine or cysteine protease, respectively, was demonstrated on human and murine melanoma cells." (PMID 31024572, 2019). "Transfection of B16F1 melanoma cells with MT1-MMP enhanced their capacity to form lung metastases in normal but not in C3-deficient C57BL/6 mice." (PMID 31024572, 2019). "We initially searched for the presence of C1q, C1s, C4 and C3 in a panel of 30 invasive malignant neoplasm specimens including 6 cases of colon adenocarcinoma, 6 cases of melanoma, 6 cases of lung adenocarcinoma, 6 cases of breast adenocarcinoma and 6 cases of pancreatic adenocarcinoma." (PMID 26831747, 2016). "In conclusion, the complement components C3, C5, C3AR1, and C5AR1 demonstrated a context-dependent association with tumor immune evasion, prognosis, and therapy response with high implicative value in melanoma, colorectal, brain, breast, stomach, and renal cancer." (PMID 34439277, 2021). "A high level of C3 expression suggested a good outcome for immune checkpoint blockade (ICB) therapy targeting PD1, CTLA4, and ACT in melanoma, but a bad outcome for ICB therapy targeting PD1 and PDL1 in GBM and bladder cancer." (PMID 37907575, 2023).
melanoma (continued). "Taken together, these data suggest that melanoma-secreted cytokines such as TGF-β and IL-1β contribute to the melanoma microenvironment by upregulating C3 expression in MAMCs, thus inducing an MC phenotype switch that negatively impacts melanoma prognosis." (PMID 35669782, 2022). "Autocrine complement C3 inhibits IL-10-mediated cytotoxic properties of tumor-infiltrating CD8 T lymphocytes through complement receptors C3aR and C5aR1, and enhances melanoma and breast cancer growth." (PMID 31001273, 2019). "Similar to the mouse melanoma model data, the S1 population (PDGFRAhi PDPNhi CD34hi) was characterized by the expression of genes involved in the regulation of immune cell recruitment (cytokines: CXCL12; complement factors: CFD, C3, C1S, CFH)." (PMID 36929873, 2023). "In vitro, we show that melanoma cell supernatants and tumor microenvironment (TME) mediators such as TGF-β, IL-33, and IL-1β induce some of the changes found in MAMCs and significantly modulate C3 expression and activity in MCs." (PMID 35669782, 2022). "Consistent with this, in a syngeneic melanoma model the lack of C1q, but not of C3 or C4, reduced the tumour growth and invasion." (PMID 26831747, 2016). "C3 had previously been described as a substrate of CTSL expressed by human melanoma cells but in those studies, C3 was not processed into C3a and C3b but rather fully degraded." (PMID 24315997, 2013). "Furthermore, the number of tryptase− C3+ cells did not significantly change with melanoma progression, while C3+ MAMCs were significantly increased in stage IV (50 cells/mm2, SD: 32.2, n = 20) in comparison to healthy C3+ MCs (21.2 cells/mm2, SD: 9.8, n = 10)." (PMID 35669782, 2022). "We used immunohistochemistry (IHC) staining and analyzed the expression of these putative biomarkers (complement component 3 (C3), complement component 5 (C5), and absent in melanoma 2 (AIM2)) based on the staining area and intensity of the color reaction to predict BEV efficacy in EOC patients." (PMID 34640548, 2021). "Thus, the fact that multiple cytokines synergize in modulating C3 expression would explain why TGF-β, IL-33, and IL-1β activity blockade did not fully inhibit the expression of C3 in MCs treated with melanoma cell culture supernatants." (PMID 35669782, 2022).
renal fibrosis (29 papers, 2016 to 2025). A final common manifestation of a wide variety of chronic kidney diseases characterized by glomerulosclerosis and tubulointerstitial fibrosis. "In this study, we observed that C3 deficiency is associated with a higher renal leptospiral load and an increased incidence of renal fibrosis after one month of chronic infection." (PMID 40236016, 2025). "For instance, C3 expression has been shown to correlate with the severity of renal fibrosis, while C3 deficiency reduced the recruitment of inflammatory cells and pro-inflammatory cytokine production." (PMID 39272977, 2024). "C3 is a critical component of the complement cascade; however recent findings have also implicated it in renal fibrosis." (PMID 36586434, 2023). "We observed a dynamic decrease in uromodulin and CFH protein levels, which were associated with the development of renal fibrosis and C3 deposition." (PMID 37047611, 2023). "C3 deficiency also suppresses the fibrotic response in models of renal fibrosis." (PMID 41324413, 2025). "Among them, the functions of Fn, Timp1, C3, Apoe, Trf, and Fbn1 were already previously thoroughly studied in renal fibrosis." (PMID 40564035, 2025). "Improved eGFR and reduced renal fibrosis and inflammation by downregulating inflammatory genes like C3, CCL2, and TNFα and modulating angiogenesis, fibrosis, inflammation, and proliferation pathways." (PMID 38929190, 2024). "In this study, we aimed to elucidate the impact of the intra-renal complement C3 in renal fibrosis by using both in vivo and in vitro research models." (PMID 39684261, 2024). "We investigated roles of twist-related protein 1 (TWIST1) in EMT phenomenon and renal fibrosis through C3 upregulation in a mouse UUO model with gene silencer pyrrole-imidazole (PI) polyamides targeting TWIST1." (PMID 36018840, 2022). "The complement system is another important pathogenic mediator in the pathogenesis of AKI, and its member C3 regulates renal fibrosis through the HMGB1/TGF-β1/Smad2/3 signaling pathway." (PMID 35872775, 2022). "TWIST1 upregulates C3 that stimulates the expression of TGF-β1, which induces the EMT phenomenon to cause renal fibrosis." (PMID 36018840, 2022). "For example, locally synthesized C3 promotes renal fibrosis via the C3a receptor in the mouse model of unilateral ureteral obstruction." (PMID 36249739, 2022). "Complement systems, such as C3, are involved in infection, with local C3 secretion by macrophages promoting renal fibrosis and defense mechanisms against intracellular bacteria." (PMID 35638785, 2022). "TWIST1 induced the EMT phenomenon and renal fibrosis by upregulation of C3 with TGF-β1 in a mouse UUO model." (PMID 36018840, 2022). "miR-92d-3p suppressed the progression of DN renal fibrosis by inhibiting the activation of the C3/HMGB1/TGF-β1 pathway and EMT." (PMID 33729484, 2021). "Excessive activation of the renal complement system can cause renal tubular interstitial cytotoxicity, in which renal tubular epithelial cells are a key target of C3, resulting in proteinuria and promotion of renal fibrosis." (PMID 34433493, 2021). "Here, we report that increased local C3 expression, mainly by monocyte/macrophages, was detected in renal biopsy specimens and was correlated with the severity of renal fibrosis (RF) and indexes of renal function." (PMID 30405606, 2018). "To determine whether C3 mediates renal fibrosis after IRI, we assessed renal pathology in C3−/− mice compared with age-matched wild-type (WT) mice." (PMID 36973754, 2023). "C3−/− resulted in amelioration of renal dysfunction by reducing podocyte damage and renal fibrosis." (PMID 36973754, 2023). "In addition, the expression of genes associated with complement and coagulation activation, such as F3, Fga, Pai1, C3, and C5ar1, was also elevated in the two different renal fibrosis models, indicating the upregulation of local renal coagulation and complement cascades in the pathogenesis of CKD." (PMID 41324413, 2025).
renal fibrosis (continued). "For instance, Research indicates that HE4 activates the NF-κB pathway by promoting C3 and MMP2/9 expression, driving renal fibrosis." (PMID 41502510, 2025). "In this research, we found that complement C3 was activated during post-AKI renal fibrosis of mice as complement C3 knockout mice can improve renal tissue inflammation and podocyte damage during AKI, reducing post-AKI renal fibrosis." (PMID 36973754, 2023). "Here, PAS staining and Masson staining showed that crocin reduced the thickness of GBM and renal fibrosis in PHN rats, and immunofluorescence staining revealed that crocin decreased the deposition of IgG, C3 and C5b-9." (PMID 37724538, 2023). "Increased production of pro-fibrotic cytokines such as MCP-1, complement protein 3 (C3), and TGF-β after AKI promotes EMT and leads to renal fibrosis and eventual progression to CKD." (PMID 35872775, 2022). "In the present study, we investigated the contributions of TWIST1 to the upregulation of C3 in the EMT phenomenon and renal fibrosis in a mouse UUO model with PI polyamides targeting TWIST1." (PMID 36018840, 2022). "We have demonstrated that complement 3 (C3) is upregulated and induces epithelial-mesenchymal transition (EMT) phenomenon and renal fibrosis in unilateral ureteral obstruction (UUO) kidney." (PMID 36018840, 2022). "During the progression of DN disease, miR-92d-3p interacts with C3 to inhibit the activation of the C3/HMGB1/TGF-β1 pathway and EMT, thereby preventing the progression of DN renal fibrosis." (PMID 33729484, 2021). "This suggests that the delayed clearance of leptospires in the absence of C3 provides prolonged stimulation, thereby promoting renal fibrosis." (PMID 41251377, 2025). "We speculate that the activation of complement C3 is thereby closely related to podocyte injury and post-AKI renal fibrosis." (PMID 36973754, 2023).